MARCHF6-DT (MARCHF6 divergent transcript)
Description:
Micropeptide that acts as a regulator of DNA repair both by preventing KLHL15-mediated ubiquitination and degradation of RBBP8/CtIP, and by promoting the poly-ADP-ribosyltransferase activity of PARP1. Prevents KLHL15-mediated ubiquitination of RBBP8/CtIP by competitively blocking the association between KLHL15 and RBBP8/CtIP. Recruited to DNA damage sites via association with poly-ADP-ribose chains, and enhances the poly-ADP-ribosyltransferase activity of PARP1.
Synonyms: PACMP; CTD-2256P15.2
Gene: Long non-coding RNA gene on chromosome 5 (10,323,547 to 10,354,117, reverse strand). Ensembl gene ENSG00000259802.
Subcellular location: Nucleus, nucleolus; Chromosome
Diseases named in the same sentence as MARCHF6-DT in open-access papers:
MARCHF6-DT is named in the same sentence as 1 disease in open-access papers, as found by Europe PMC text mining. Sharing a sentence is not in itself a finding about the gene and the disease.
MARCHF6-DT shares sentences with these, for which no sentence is quoted: cancer (4 papers).